C9 (complement C9)
Description:
Pore-forming component of the membrane attack complex (MAC), a multiprotein complex activated by the complement cascade, which inserts into a target cell membrane and forms a pore, leading to target cell membrane rupture and cell lysis. The MAC is initiated by proteolytic cleavage of C5 into complement C5b in response to the classical, alternative, lectin and GZMK complement pathways. The complement pathways consist in a cascade of proteins that leads to phagocytosis and breakdown of pathogens and signaling that strengthens the adaptive immune system. Constitutes the pore-forming subunit of the MAC complex: during MAC assembly, C9 associates with the C5b8 intermediate complex, and polymerizes to complete the pore.
Synonyms: ARMD15; C9D
Tractability: Small molecule: a high-quality ligand is known. Antibody: UniProt places it where antibodies can reach, with high confidence; its Gene Ontology location is reachable by antibodies, with high confidence; UniProt predicts a signal peptide or a membrane-spanning region. PROTAC: ubiquitination databases record sites on it; its protein half-life has been measured; a small molecule that binds it is known.
Gene: Protein-coding gene on chromosome 5 (39,283,982 to 39,371,324, reverse strand). Ensembl gene ENSG00000113600.
Subcellular location: Secreted; Target cell membrane
Pathways (Reactome):
Immune System: Regulation of Complement cascade; Terminal pathway of complement
Gene Ontology:
Molecular function: protein binding; wide pore channel activity
Biological process: cell killing; complement activation; complement activation, GZMK pathway; killing of cells of another organism; protein homooligomerization; positive regulation of immune response; immune response; transmembrane transport
Cellular component: blood microparticle; extracellular exosome; extracellular region; membrane attack complex; other organism cell membrane; plasma membrane
Genetic constraint (gnomAD): Loss-of-function variants: 36 observed, 38.86 expected, observed/expected ratio (o/e) 0.93, 90% interval 0.71 to 1.22. The upper end of that interval is the gene's LOEUF score, 1.22, which puts it in group 5 of 6, group 1 being the genes least tolerant of losing a copy. Missense variants: 480 observed, 441.85 expected, observed/expected ratio (o/e) 1.09, 90% interval 1.01 to 1.17. Synonymous variants: 151 observed, 153.71 expected, observed/expected ratio (o/e) 0.98, 90% interval 0.86 to 1.12.
Homologues: Orthologues: chimpanzee C9 (99% identical), macaque C9 (92% identical), dog C9 (72% identical), pig C9 (70% identical), rabbit C9 (70% identical), rat C9 (65% identical), mouse C9 (58% identical), tropical clawed frog c9 (42% identical), zebrafish c9 (39% identical). Paralogues in human: C8A (27% identical), C8B (25% identical), C6 (25% identical), C7 (24% identical), CFH (15% identical), CSMD2 (14% identical), CSMD1 (14% identical), CSMD3 (13% identical), PAPPA2 (13% identical), PAPPA (13% identical), PRF1 (12% identical), SVEP1 (12% identical), and 27 more.
Diseases named in the same sentence as C9 in open-access papers:
C9 is named in the same sentence as 162 diseases in open-access papers, as found by Europe PMC text mining. Sharing a sentence is not in itself a finding about the gene and the disease. The quoted sentences say what the papers report.
COVID-19 (18 papers, 2021 to 2026). A disease caused by infection with severe acute respiratory syndrome coronavirus 2. "Our results further showed that the complement components C4b-binding protein and its alpha chain [P04003], as well as C9 [P02748] were elevated in the post-COVID-19 patient group compared to the uninfected." (PMID 36077551, 2022). "We similarly showed that pregnant participants with severe COVID-19 had upregulation of C3/C5 convertase, complement component C2, complement component C9, and complement C1q subcomponent subunit C, indicating increased complement activation." (PMID 36383608, 2022). "LGALS3BP abundance in COVID-19 patients closely correlated with proteins and regulators of the complement cascade (C6, C9, C4BPA, and C4BPB)." (PMID 34099652, 2021). "Notably, C9 and LBP were repeatedly identified across WGCNA, DiNA, and differential expression analyses, underscoring their robust association with severe COVID-19-associated molecular network remodeling." (PMID 42193140, 2026). "YYJH regulates the key molecule complement component 9 (C9) in acute pharyngitis, which is primarily enriched in pathways related to the complement pathway, systemic lupus erythematosus, prion disease, coronavirus disease—COVID-19, and amoebiasis." (PMID 40855320, 2025). "Similarly, another study on patients with severe COVID-19 found elevated deposits of C5a to C9 in biopsies of skin and lung tissue." (PMID 36077551, 2022). "In addition, complement factors of the terminal complement complex (TCC), C5, C6, C7, C8 and C9, were significantly increased in neutrophils from intermediate and patients with severe COVID-19." (PMID 34403366, 2021). "Moreover, we found an 2.5-fold increase of C9 in non-critical patients and a down-regulation of CFH; these findings suggest that, in critical COVID-19 patients, the C9 complement component might be impaired due to SARS-CoV-2 infection, as has already been shown for the hepatitis C virus." (PMID 33693030, 2021). "We found levels of the complement component 2 (C2, protein ID P06681) and complement component 9 (C9, Protein ID P02748) proteins were elevated in the severe and non-severe COVID-19 groups as compared to the healthy group." (PMID 35842456, 2022). "Similarly, in previous reports, FGB, FGG, complements C4, C3, C5, C2, C9, and complement C1q subcomponent subunits A, B, and C (C1QA, C1QB and C1QC) were found to be upregulated in the lung tissues of patient with COVID-19." (PMID 38882332, 2024). "Concentrations of select chemokines (CXCL8, CXCL10, CCL2, CCL3, CCR1) and complement factors (C2, C9, CFD, C4BPA, C5AR1, CR1) were examined at mRNA and protein levels with regard to a COVID-19 course (ICU vs. non-ICU group) and CMV status at different time intervals." (PMID 36232655, 2022).
frontotemporal dementia (15 papers, 2018 to 2025). Frontotemporal dementia (FTD) comprises a group of neurodegenerative disorders, characterized by progressive changes in behavior, executive dysfunction and language impairment, as a result of degeneration of the medial prefrontal and frontoinsular cortices. "The most prevalent genetic cause of both amyotrophic lateral sclerosis and frontotemporal dementia is a (GGGGCC)n nucleotide repeat expansion (NRE) occurring in the first intron of the C9orf72 gene (C9)." (PMID 38684907, 2024). "The most common genetic cause of both amyotrophic lateral sclerosis (ALS) and frontotemporal dementia (FTD) has been proven to be a large hexanucleotide repeat expansion (G4C2)n within intron 1 of C9orf72 (C9)." (PMID 34491551, 2022). "Cytoplasmic aggregates of the predominantly nuclear TAR DNA-binding protein 43 (TDP-43) are a pathological hallmark of amyotrophic lateral sclerosis (ALS) and frontotemporal dementia (FTD) cases caused by G4C2 hexanucleotide repeat expansions in C9orf72 (C9-ALS/FTD)." (PMID 40581653, 2025). "A repeat expansion in the C9orf72 (C9) gene is the most common genetic cause of amyotrophic lateral sclerosis (ALS) and frontotemporal dementia (FTD)." (PMID 37714849, 2023). "The C9orf72 mutation (C9+) is also a common cause of familial frontotemporal dementia (FTD)." (PMID 30568632, 2018). "Nuclear depletion and cytoplasmic aggregation of the TAR DNA-binding protein 43 (TDP-43) is a pathological hallmark of amyotrophic lateral sclerosis (ALS) and frontotemporal dementia (FTD) patients caused by a hexanucleotide repeat expansion mutation in the C9ORF72 gene (C9-ALS and C9-FTD)." (PMID 37466726, 2023). "One of the most common genetic causes for both ALS and frontotemporal dementia (FTD), a closely related neurodegenerative condition that shares both genetic and pathological signs with ALS, is a GGGGCC hexanucleotide repeat expansion (HRE) in the C9ORF72 gene (C9-ALS)." (PMID 38664831, 2024). "Researchers using Cynomolgus monkeys have been able to create a primate model of C9orf72 related dipeptide repeats (DPRs) and show that poly (PR) DPRs are sufficient to induce C9-ALS/frontotemporal dementia (FTD)-like symptoms in primates." (PMID 39280794, 2024). "The most common genetic cause of amyotrophic lateral sclerosis (ALS) and frontotemporal dementia (FTD) is a hexanucleotide repeat expansion (HRE) intronic to C9orf72 (C9-ALS/FTD)." (PMID 39421070, 2024). "An expansion of hexanucleotide GGGGCC (G4C2) repeat within the first intron of C9orf72 gene is the most common cause of familial ALS as well as frontotemporal dementia (FTD), commonly termed as C9-ALS/FTD." (PMID 33129345, 2020). "The most common of these is a -(G4C2)n- nucleotide repeat expansion (NRE) in a non-coding region of the C9orf72 gene (C9), which accounts for up to 20% of all ALS cases, as well as a subset of frontotemporal dementia (FTD) cases." (PMID 38684907, 2024).
amyotrophic lateral sclerosis (13 papers, 2019 to 2025). Amyotrophic lateral sclerosis (ALS) is a neurodegenerative disease characterized by progressive muscular paralysis reflecting degeneration of motor neurons in the primary motor cortex, corticospinal tracts, brainstem and spinal cord. "In works that involved extending these studies to other diseased loci, Pribadi and colleagues attempted to remove methylation in the C9orf72 locus by gene editing in C9-related Amyotrophic lateral sclerosis and/or frontotemporal degeneration (ALS/FTD)." (PMID 33921346, 2021). "GGGGCC hexanucleotide repeat expansion (HRE) in the non-coding region of chromosome 9 open reading frame 72 (C9orf72) (C9-HRE) is the major genetic cause of familial FTLD (12–48%) and amyotrophic lateral sclerosis (ALS) (24–46%) cases and 6–20% of sporadic cases for both diseases." (PMID 31156371, 2019).
lung carcinoma (12 papers, 2011 to 2024). "Epitope profiling enabled the classification of hypothetical C9 proteoforms through differential association with lung cancer." (PMID 37762663, 2023). "With the ultimate goal to explore C9 proteoforms and their relevance to lung cancer, here we report plasma C9 epitope-associated molecular heterogeneity in plasma samples of lung cancer patients and control subjects." (PMID 37762663, 2023). "In this report, we test epitope-specific mAbs of plasma C9 for which protein we previously detected epitope-dependent association with lung cancer (LC)." (PMID 37762663, 2023). "The elevated plasma levels of C3, C9 and C4d complement proteins were associated with shorter survival of patients with lung cancer." (PMID 30841875, 2019). "Many protein biomarkers, such as serum amyloid A, Hp, and complement components 9 (C9) and 4d (C4d), have been identified and validated in serum or plasma samples of lung cancer." (PMID 36721112, 2023). "Nevertheless, the concrete mechanisms of downregulation of C9 in TAMs in hypoxic environment were needed to further study to more clearly understand the strategy of lung cancer cells eluding CDC." (PMID 29900010, 2018). "C9 is downregulated in alveolar TAMs, leading to lung cancer progression." (PMID 36138066, 2022). "Interestingly, several of the pulmonary TB markers have previously been reported as part of a 7-protein classifier for lung cancer, including C9, CRP, and carbonic anhydrase, and C9 and kallistatin were part of a 13-marker signature of mesothelioma." (PMID 28794177, 2017). "Protein epitome profiling or epitomics are promising for coprecipitated protein composition and specific posttranslational modification, and while this could classify hypothetical C9 proteoforms in lung cancers, its application is imperative for treatment of NSCLC." (PMID 38841622, 2024). "The second panel, comprising CFHR5, C9, and MBL2 proteins, shows potential in evaluating the occurrence of metastasis in patients with early-stage lung cancer." (PMID 37953280, 2023). "We have also previously reported certain acute-phase proteins as lung cancer biomarkers: serum amyloid A (SAA), haptoglobin (Hp) β chain and complement 9 (C9)." (PMID 30336636, 2018). "We show that three independent epitopes of C9 recognized by mAbs (BSI0639, BSI0581 and BSI0449) exhibit markedly different associations with lung cancer: neutral (BSI0449), negative (BSI0639) and positive (BSI0581)." (PMID 37762663, 2023). "The proteins related to host defense, CRP, C9 and SERPINA3, are elevated in lung cancer and may arise from tumor-induced stromal inflammation." (PMID 25114662, 2014).
colorectal cancer (9 papers, 2012 to 2025). A primary or metastatic malignant neoplasm that affects the colon or rectum. "Previous investigations have revealed that the levels of C9 protein in the plasma of patients with gastric and colorectal cancers exhibit a substantial increase." (PMID 37953280, 2023). "A peptide peak with 622 m/z (RT 56.8 min) was annotated as a fragment of C9 specific to colorectal cancer patients (P = 3.0 × 10−5, paired t-test)." (PMID 22844596, 2012). "There was a significant difference in C9 expression in plasma from colorectal cancer patients and from healthy controls (P = 1.43 × 10−12, Student's t-test)." (PMID 22844596, 2012). "Plasma complement factor 9 has been identified as a biomarker for gastric, lung and colorectal cancers; however, none of the previous reports dissected C9 to explore epitome-level association." (PMID 37762663, 2023). "In addition to our work in EAC, proteomic and glycoproteomic cancer biomarker discovery studies have reported plasma/serum C9 as a biomarker for colorectal cancer, gastric cancer, squamous cell lung cancer and glioblastoma." (PMID 34201241, 2021). "log(P/(1-P) = -7.8709 + 4.5956 × IGFBP2 + 0.2732 × ITIH3 + 0.0909 × LRG1 + 0.1015 × C9 -3.2205 × CNDP1 + 0.0239 × ORM1 + 0.0811 × SERPINA1, where P is a value between 0 and 1 that represents the probability of the event (colorectal cancer)." (PMID 38383428, 2024).
complement deficiencies (8 papers, 2010 to 2025). "Our findings with C9 align with epidemiologic evidence that C9 deficiencies more modestly predispose individuals to Neisseria compared to other terminal complement deficiencies." (PMID 40162779, 2025). "C7 deficiency is the second most frequent complement deficiency in Japan, after C9 deficiency, affecting approximately one in 10,000 individuals." (PMID 41195038, 2025). "In contrast, C9 deficiency has been documented in some Japanese patients with terminal complement deficiency." (PMID 35084692, 2022). "Generally, complement deficiencies are inherited as autosomal recessive traits (homozygous or compound heterozygous), except for properdin (X-linked recessive pattern), C1 inhibitor (autosomal dominant pattern) and C9, whose inheritance pattern is undetermined, according to OMIM." (PMID 36510129, 2022). "It has been suggested that C3b opsonization contributes to host defense as patients with C3 complement deficiency suffer from Hib infections rather than individuals with membrane attack complex (MAC, C5b-C9) deficiencies." (PMID 36578495, 2022).
age-related macular degeneration (6 papers, 2015 to 2022). Age-related loss of vision in the central portion of the retina (macula), secondary to retinal degeneration. "Moreover, similar to C9, diverse variants of C2 and C3 proteins are associated with age-related macular degeneration." (PMID 35625664, 2022). "For example, in age-related macular degeneration (AMD), a retinal disease clinically and pathologically linked to LOAD, genes encoding complement components C2, C3, FB and C9, and regulators FH and FHR4, all contribute to risk." (PMID 33804666, 2021).
Alzheimer disease (6 papers, 2006 to 2025). A progressive, neurodegenerative disease characterized by loss of function and death of nerve cells in several areas of the brain leading to loss of cognitive function such as memory and language. "APOA4 upregulation has been associated with PD, and C9 has been shown to be higher expressed in PD patients as compared to Alzheimer’s Disease patients." (PMID 34535682, 2021). "Complement C9 deposition in the hippocampus contributes to responses to brain injury and Alzheimer’s disease and is induced in human neuronal cells by inflammatory stimuli." (PMID 23936146, 2013).
diabetes (5 papers, 2016 to 2025). "Further, urinary complement C3 and C9 are negatively correlated with eGFR and associated with progressive renal decline in patients with diabetes." (PMID 37240105, 2023). "These proteins we considered to be diabetes-typical, including two members of the complement system, C4 and C9, ApoE, fibrillin, fibronectin, TIMP-3 and Prolargin/PRELP, a proteoglycan." (PMID 29284024, 2017). "Glycation of the complement inhibitor CD59 renders the glycoprotein unable to bind C9 and thus unable to inhibit the formation of the MAC, which may also contribute to excessive complement-mediated damage in diabetes." (PMID 37240105, 2023). "The data allowed us to build models that could distinguish DKD from diabetes (AUC = 0.928) with 2 proteins (ALB, AFM), and distinguish DKD3 from DKD4 (AUC = 0.949) with 3 proteins (ANXA7, APOD, C9)." (PMID 34963468, 2021).
primary immunodeficiency (5 papers, 2015 to 2025). "No C9 deficient patients were detected in this series, in keeping with the absence of this immune deficiency in the UK and other European Primary Immunodeficiency registries." (PMID 35084692, 2022).
Stroke (5 papers, 2010 to 2025). Sudden impairment of blood flow to a part of the brain due to occlusion or rupture of an artery to the brain. "In a hypoxia-ischemia model in neonatal rats, C5b-9 was neurotoxic because the deficiency of C9 reduced brain infarct volume after 24 hours of stroke, while C9 administration reversed the result." (PMID 31011487, 2019). "Data from human patients who died from a stroke showed a prominent deposition of complement C1q, C3c, C4d, and C9 components in the ischemic brain." (PMID 39531190, 2025). "Specifically, elements of the alternative pathway of complement system and MAC proteins, i.e., CFI, C6, C8A, C8G, C9 were found to be activated but also undergoing regulation at 3 months post-stroke." (PMID 32849183, 2020). "In contrast, stroke induced a significant increase in maximal circulating concentrations of C1q, C5 and C9 in both IL-1Ra and placebo treated patients measured in the first seven days after stroke in comparison to non-stroke controls." (PMID 31700615, 2019). "Maximum circulating concentration of complement components associated with the classical and lectin pathways of activation, C1q, C2 and C4b, and end stage mediators common to all pathways, C5 and C9, were increased in the first seven days after stroke in comparison to non-stroke controls." (PMID 31700615, 2019). "Moreover, a stroke study in neonatal rats, naturally lacking C9 - which is part of the terminal MAC - demonstrated an increase of infarct volumes in neonatal rats when purified C9 was injected." (PMID 20202211, 2010).
viral infection (5 papers, 2013 to 2023). "Our novel variant identified in perforin 1 (PRF1) encodes complement component C9 structural similar protein that assembles into membrane pores in response to virus infection and cancer." (PMID 34070492, 2021). "The Complement System pathway identified four proteins: C4BP, C8, and C9 as upregulated and C1q as downregulated while the membrane attack complex is activated, which is common in an acute response against viral infection." (PMID 34264436, 2022). "The complement system is activated via multiple pathways, leading to the production of C3a, C5a, and C5b-C9 membrane attack complex (MAC) that are increasingly recognized as mediators of protection or pathology in a variety of viral infections." (PMID 34220748, 2021). "The data with C9 is consistent with what has been determined for in vivo protection from viral infection by neutralizing antibodies, while C9 at 0.25 mg/kg could also protect over half of animals from CHIKV-driven lethality." (PMID 24069479, 2013).